ZNF512B (zinc finger protein 512B)
Description:
Involved in transcriptional regulation by repressing gene expression. Associates with the nucleosome remodeling and histone deacetylase (NuRD) complex, which promotes transcriptional repression by histone deacetylation and nucleosome remodeling. Sequence-specific DNA-binding protein that recognizes repetitive and non-consecutive TTC sequences in pericentric repeat and initiate heterochromatin formation through interaction with SUV39H1/2 methyltransferases which catalyze histone H3K9 methylation (By similarity).
Synonyms: GM632; MGC149845; MGC149846
Tractability: Small molecule: a structure with a bound ligand is known. PROTAC: ubiquitination databases record sites on it.
Gene: Protein-coding gene on chromosome 20 (63,956,704 to 63,969,962, reverse strand). Ensembl gene ENSG00000196700.
Subcellular location: Nucleus; Chromosome
Subcellular location (Human Protein Atlas): Nucleoplasm
Pathways (Reactome):
Signal Transduction: RHOV GTPase cycle
Gene Ontology:
Molecular function: DNA-binding transcription repressor activity, RNA polymerase II-specific; protein binding; RNA polymerase II transcription regulatory region sequence-specific DNA binding; DNA binding; zinc ion binding
Biological process: negative regulation of miRNA transcription; constitutive heterochromatin formation; negative regulation of transcription by RNA polymerase II; regulation of gene expression
Cellular component: nucleoplasm; chromosome; nucleus
Genetic constraint (gnomAD): Loss-of-function variants: 25 observed, 84.48 expected, observed/expected ratio (o/e) 0.3, 90% interval 0.22 to 0.41. The upper end of that interval is the gene's LOEUF score, 0.41, which puts it in group 1 of 6, group 1 being the genes least tolerant of losing a copy. Missense variants: 1,060 observed, 1,195.7 expected, observed/expected ratio (o/e) 0.89, 90% interval 0.84 to 0.93. Synonymous variants: 524 observed, 477.91 expected, observed/expected ratio (o/e) 1.1, 90% interval 1.02 to 1.18.
Homologues: Orthologues: chimpanzee ZNF512B (99% identical), macaque ZNF512B (98% identical), pig ZNF512B (87% identical), rat Zfp512b (86% identical), mouse Zfp512b (86% identical), guinea pig ZNF512B (85% identical), dog SAMD10 (79% identical), rabbit ZNF512B (74% identical), tropical clawed frog znf512b (40% identical), zebrafish znf512b (38% identical), Drosophila melanogaster nahoda (21% identical), Caenorhabditis elegans C09F9.2 (10% identical), and 3 more. Paralogues in human: ZNF512 (24% identical), GGN (10% identical).
Diseases named in the same sentence as ZNF512B in open-access papers:
ZNF512B is named in the same sentence as 3 diseases in open-access papers, as found by Europe PMC text mining. Sharing a sentence is not in itself a finding about the gene and the disease. The quoted sentences say what the papers report.
cancer (1 paper, 2024). A tumor composed of atypical neoplastic, often pleomorphic cells that invade other tissues. "Endogenous ZNF512B mRNA is expressed ubiquitously at low levels; however, brain and certain cancer tissues exhibit elevated ZNF512B gene expression." (PMID 39460621, 2024). "Our study might have implications for diseases in which ZNF512B expression is deregulated, such as cancer and neurodegenerative diseases, and hints at the existence of more proteins as potential NuRD interactors." (PMID 39460621, 2024).
ZNF512B also shares sentences with these, for which no sentence is quoted: amyotrophic lateral sclerosis (1 paper); neurodegenerative disease (1).